FBLN2 (fibulin 2)
Diseases named in the same sentence as FBLN2 in open-access papers (continued):
Sharing a sentence is not in itself a finding about the gene and the disease.
meningioma (5 papers, 2017 to 2025). A generally slow growing tumor attached to the dura mater. "Expanding the study to include a larger sample cohort and longer (5–10 years) follow up period may improve the diagnostic accuracy of Fibulin-2 for differentiating between grade II and grade I meningiomas." (PMID 33429944, 2021). "While this is primarily a diagnostic biomarker study, the mechanism underlying Fibulin-2 (FBLN2) expression in meningiomas will need to be investigated with further in vitro studies such as the knock-down of the FBLN2 gene and downregulation of Fibulin-2 expression in grade II meningiomas." (PMID 33429944, 2021). "However, the mechanism underlying the Fibulin-2 expression patterns observed in this study remains unclear but may be related to the brain invasive properties of the higher grade meningiomas." (PMID 33429944, 2021). "Fibulin-2 has an emergent role in carcinogenesis and high-grade gliomas and has been recently proposed as a prognostic biomarker for meningiomas." (PMID 36048342, 2022). "Compared to the grade I meningioma patients, Fibulin-2 plasma concentrations were significantly higher in grade II patients (p = 0.03)." (PMID 33429944, 2021). "We found significantly higher plasma concentrations of Fibulin-2 in grade II meningioma patients compared to the grade I cohort." (PMID 33429944, 2021). "When differentiating between grade II and I meningiomas, a Fibulin-2 blood plasma cut off value > 2.5 ng/mL has a 95% specificity for identifying patients with grade II meningiomas over those with grade I tumours." (PMID 33429944, 2021). "To assess the efficacy of Fibulin-2 as a non-invasive biomarker difference between grade I and II meningiomas, we carried out ELISA experiments on blood (plasma) samples from meningioma patients." (PMID 33429944, 2021). "By performing MS proteomics validated with Western Blotting, we found that primary cells derived from grade II meningiomas expressed significantly higher levels of Fibulin-2 when compared to levels in grade I meningioma cells." (PMID 33429944, 2021). "We also suggest the evaluation of Fibulin-2 in grade III meningioma patients, though a large multicentre study will be required due to the small incidence/prevalence of grade III meningiomas." (PMID 33429944, 2021). "A total of 87 grade I and 91 grade II different meningioma cells, tissue and plasma samples were used for the various experimental techniques employed to assess Fibulin-2 expression." (PMID 33429944, 2021). "This also revealed a higher FBLN2 expression (Log2Fc of Gd II vs. Gd I = 5.46; p < 0.01) in grade II meningiomas compared to grade I." (PMID 33429944, 2021). "In this study, we identified Fibulin-2 as a novel biomarker for differentiating between grade II and I meningiomas and demonstrated higher expression in grade II meningioma (primary cells and tissue), at protein and gene expression levels." (PMID 33429944, 2021). "IHC revealed more intense staining in the grade II tumours compared to grade I, while RT-qPCR showed that the FBLN2 gene is also overexpressed in grade II meningiomas compared to grade I, confirming the expression patterns observed in the meningioma cells." (PMID 33429944, 2021). "Fibulin-2 staining was observed to be diffusely cytoplasmic in tumour cells, and more intense in the grade II tumours, with 64% of grade II meningiomas staining strongly compared to 40% in the grade I cohort." (PMID 33429944, 2021). "Mass spectrometry proteomic analysis identified Fibulin-2 as a differentially expressed protein between grade I and II meningioma cell cultures." (PMID 33429944, 2021). "In this study, we assessed Fibulin-2 as a biomarker for differentiating between grade II and grade I meningiomas, by evaluating its expression in meningioma cells, tissue and blood plasma levels." (PMID 33429944, 2021).
meningioma (continued). "A total of 178 grade I and II different meningioma cells, tissue and plasma samples (sometimes from the same patient) were used for the various experimental techniques employed to assess Fibulin-2 expression." (PMID 33429944, 2021). "In this study, we identified the calcium binding extracellular matrix glycoprotein, Fibulin-2, via mass-spectrometry-based proteomics, assessed its expression in grade I and II meningiomas and explored its potential as a grade II biomarker." (PMID 33429944, 2021). "We also confirmed higher plasma Fibulin-2 concentrations in blood samples from grade II meningioma patients, compared to those from grade I meningioma patients." (PMID 33429944, 2021). "In order to further evaluate the expression profiles of Fibulin-2 (FBLN2) in these meningioma grades, we carried out gene expression studies on 26 grade I and 23 grade II meningioma tumour tissues via RT-qPCR." (PMID 33429944, 2021). "The trend of Fibulin-2 expression observed in plasma from these patients may serve as a useful non-invasive biomarker when differentiating between both meningioma grades." (PMID 33429944, 2021). "Fibulin-2 levels were further evaluated in meningioma cells using Western blotting and Real-time Quantitative Polymerase Chain Reaction (RT-qPCR); in meningioma tissues via immunohistochemistry and RT-qPCR; and in plasma via Enzyme-Linked Immunosorbent Assay (ELISA)." (PMID 33429944, 2021). "This confirmed Fibulin-2 overexpression in grade II compared to grade I meningioma primary cells." (PMID 33429944, 2021). "We then assessed Fibulin-2 expression patterns in grade I and II meningioma tissue." (PMID 33429944, 2021). "Real-time Quantitative Polymerase Chain Reaction (RT-qPCR) gene expression studies on a validation sample set showed that FBLN2 gene expression was significantly higher (Log2Fc of Gd II vs. Gd I = 5.36; p < 0.05) in grade II (n = 6) versus grade I (n = 7) meningioma cells." (PMID 33429944, 2021). "This study suggests that elevated Fibulin-2 might be a novel grade II meningioma biomarker, when differentiating them from the grade I tumours." (PMID 33429944, 2021). "In this study, the observed increase in Fibulin-2 (FBLN2) expression in grade II meningiomas may be due to the protein stabilizing the tumoural ECM, promoting an environment that favours hypercellularity, cell proliferation and (brain) invasion." (PMID 33429944, 2021). "However, there was a notable overlap in the spread of Fibulin-2 levels between grades, though we found that a cut-off value > 2.5 ng/mL was highly specific for patients with grade II meningiomas." (PMID 33429944, 2021). "Recently, it was found that FBLN2 was significantly more expressed in the plasma of patients with meningioma grade II, compared to patients with grade I meningioma, suggesting that FBLN2 might be a non-invasive biomarker for this disease." (PMID 34769264, 2021). "RT-qPCR confirmed higher FBLN2 expression in the grade II meningioma cells." (PMID 33429944, 2021). "Notably, FBLN2 levels are elevated in blood of meningioma patients and CSF of severe TBI patients, which may in part reflect demyelination processes in the CNS." (PMID 40524252, 2025). "A prospective study assessing preoperative and postoperative plasma Fibulin-2 levels will provide more data on its potential role as a biomarker for monitoring progression (in 19.5–46% of patients treated for a recurrence) of grade I meningiomas or recurrence (in 39–58%) of grade II meningiomas." (PMID 33429944, 2021). "We also found a significant correlation between high plasma fibulin-2 levels and more aggressive methylation classes, irrespective of meningioma grade." (PMID 33429944, 2021). "Five genes that were down-regulated in the meningiomas compared to the control tissue included AQP1 (aquaporin 1), FRZB (Frizzled b), PECAM1 (platelet and endothelial cell adhesion molecule 1), PDGFRL (platelet-derived growth factor receptor-like), and FBLN2 (fibulin 2)." (PMID 29073243, 2017).
Myocardial fibrosis (5 papers, 2017 to 2025). "Lastly, fibulins—especially circulating Fibulin-2—are suggested to correlate with myocardial fibrosis in HCM, adding further value to the pool of ECM-related biomarkers in cardiac disease management." (PMID 40843168, 2025). "Additionally, the role of FBLN2 has been also studied in a murine model of myocardial fibrosis induced by chronic infusion of pressor doses of angiotensin II showing that the fibrosis degree decreases in Fbln2-/- mice." (PMID 34440261, 2021). "According to Shaukat’s study, the expression of Fbln2 is a key regulator of angiotensin II-induced TGF-β signaling and subsequent myocardial fibrosis." (PMID 37055764, 2023). "While research on FBLNs in HCM is not extensive, recent reports indicated that FBLN2 plays an essential role in Ang II-induced TGF-β signaling and subsequent myocardial fibrosis." (PMID 40843168, 2025).
pancreatic cancer (5 papers, 2013 to 2021). "FBLN2 interacts with MUC4, leading to a breach of the basement membrane (BM), which promotes the invasion of pancreatic cancer." (PMID 34769264, 2021). "FBLN2, FBLN3, and FBLN5 have been shown to regulate Notch, Insulin Growth Factor receptor (IGF1R), EGFR signaling pathways, respectively, in glioma, lung, and pancreatic cancers." (PMID 32719793, 2020).
cardiac hypertrophy (4 papers, 2018 to 2021). "For example no report was found for the role of proteolipid protein 2 in myocardial hypertrophy, and very few reports investigating whether fibulin 2 contributes to cardiac remodeling." (PMID 29872491, 2018). "In the angiotensin II (Ang II) infusion model, absence of fibulin-2 inhibits Ang II-induced myocardial hypertrophy and fibrosis in vivo with suppression of TGF-β signaling, indicating a critical role of fibulin-2 in Ang II-induced TGF-β activation and its downstream signaling." (PMID 30227601, 2018).
colorectal cancer (4 papers, 2010 to 2024). A primary or metastatic malignant neoplasm that affects the colon or rectum. "In addition, EMILIN2 and SALL1 also show frequent methylation in colorectal cancer and FBLN2 shows frequent tumour-specific methylation in prostate cancer." (PMID 20205715, 2010). "In addition we found that EMILIN2, FBLN2 and SALL1 were also frequently methylated in other common epithelial cancers, EMILIN2 and SALL1 in colorectal cancer and FBLN2 in prostate cancer." (PMID 20205715, 2010).
Stroke (4 papers, 2019 to 2024). Sudden impairment of blood flow to a part of the brain due to occlusion or rupture of an artery to the brain. "Key EMT-related genes that were downregulated in female MMP-3 KO stroke brains included Fbln5, Fbln1, Fbln2, and Tgfb1." (PMID 39000490, 2024). "Both male and female MMP-3 KO stroke brains showed decreased expression of genes involved in fibulin signaling (Fbln1, Fbn1, Fbln2, Fbln5), which are known to induce EMT during embryonic development." (PMID 39000490, 2024). "Key EMT-related genes that were downregulated in MMP-3 KO males included Fbn1, Fbln1, Tgfb1, Tgfbr3, Snai2, and Fgf2, while female MMP-3 KO stroke brains showed downregulation of Fbln5, Fbln1, Fbln2, and Tgfb1." (PMID 39000490, 2024). "We have identified fibulin-2 (FBLN2) as a highly upregulated ECM component in lesions of MS and stroke and in proteome databases of Alzheimer's disease and traumatic brain injury." (PMID 38743490, 2024).
acute lymphoblastic leukemia (3 papers, 2010 to 2021). Leukemia with an acute onset, characterized by the presence of lymphoblasts in the bone marrow and the peripheral blood. "In another report, FBLN2 locus was high methylated in breast, childhood acute lymphoblastic leukemia, and other common epithelial cancers (lung, colorectal, and prostate)." (PMID 24949431, 2014).
atherosclerosis (3 papers, 2015 to 2025). A disease characterized by the build-up of fatty material and calcium deposition in the arterial wall resulting in partial or complete occlusion of the arterial lumen. "Fibulin 2 has important features in connection with atherosclerosis." (PMID 26207907, 2015).
Cognitive impairment (3 papers, 2019 to 2022). Abnormal cognition is characterized by deficits in thinking, reasoning, or remembering. "Reduced Fbln2 alleviates the state of cognitive impairment and neural function in mice with chronic unpredictable mild stress (CUMS) through inhibiting the TGF-β1 signaling pathway." (PMID 35431783, 2022). "In the mouse model of depression, miR-192-5p rescues cognitive impairment and restores neural functions by enhancing synaptic transmission and neuronal regeneration via Fbln2/TGF-β1 signaling." (PMID 32919404, 2021).
depression (3 papers, 2021 to 2022). "Among the 36 mRNAs associated with the ceRNA network, 3 mRNAs had been reported to be related to depression (DDIT4, S100B, Fbln2)." (PMID 35431783, 2022). "In the study of depression, some scholars have demonstrated that the up-regulated expression level of miR-192-5p inhibits the activation of TGF-β1 signaling pathway by binding to Fbln2, thereby improving cognitive impairment and strengthening neurological function in the mouse model of depression." (PMID 36406755, 2022).
heart failure (3 papers, 2013 to 2019). Inability of the heart to pump blood at an adequate rate to meet tissue metabolic requirements. "Enhanced TGF-β activation and downstream signaling are noted in combination with fibulin-2 upregulation in advanced human heart failure myocardium." (PMID 30227601, 2018). "Collectively, it is plausible that ECM environment altered by upregulated fibulin-2 contributes, in part, to the pathogenesis of human heart failure via enhancing myocardial TGF-β activation via positive feedback loop." (PMID 30227601, 2018). "The significance of this observation is strengthened by data from human samples showing that Fbln2 protein expression is significantly increased in hypertrophic hearts, suggesting that it may be a key player in the development of heart failure in humans." (PMID 23612897, 2013).
Hypertension (3 papers, 2012 to 2021). The presence of chronic increased pressure in the systemic arterial system. "We note that five of seven FBLN2 variant carriers also have a diagnosis of systemic hypertension." (PMID 33971972, 2021). "A recent study reported association between a genetic marker for fibulin-2 and hypertension, lending support to the hypothesis that members of the fibulin family could be causally involved in arterial wall changes." (PMID 23866070, 2013). "Fibulin 2 is an extracellular matrix scaffold protein involved in arterial stiffness and, hence, the fibulin 2 (FBLN2) gene may be a candidate for hypertension susceptibility." (PMID 22912785, 2012). "Our results provide the first evidence for FBLN2 as a new gene associated with hypertension." (PMID 22912785, 2012). "Five of seven carriers also have a diagnosis of systemic hypertension (HTN), and it is possible that gene damaging variants in FBLN2 contribute to the development of HTN." (PMID 33971972, 2021). "Our results may provide the first evidence for FBLN2 as a new gene associated with hypertension." (PMID 22912785, 2012). "Most of the FBLN2 and PDGFD variant carriers have comorbidities typical of adult IPAH patients, including hypertension, hypothyroidism, other pulmonary diseases, and metabolic diseases." (PMID 33971972, 2021). "In this candidate gene study, we have shown that variations in FBLN2 gene (rs3732666 and rs1061376) are associated with lower levels of SBP and decreased risk of hypertension." (PMID 22912785, 2012). "We believe that changes either in the structure of fibulin 2, or in its quantitative levels, could be a new mechanism leading to hypertension." (PMID 22912785, 2012). "We hypothesize that changes either in the structure of fibulin 2, or in its quantitative levels, could be a new mechanism leading to hypertension." (PMID 22912785, 2012). "Hence, we can hypothesize that different concentrations of fibulin 2 or a change in its structure may contribute to the development of hypertension, either by stiffening the vascular wall or by altering cellular signal transduction." (PMID 22912785, 2012). "A change in structure of fibulin 2 may prevent an appropriate build-up of elastic fibers and a correct assembly of the extracellular matrix in the vascular wall; the consequence being an alteration in the structure of the vascular wall that favors hypertension." (PMID 22912785, 2012).
invasive breast carcinoma (3 papers, 2018 to 2024). A carcinoma that infiltrates the breast parenchyma. "Invasive mixed mucinous breast cancer showed a significant downregulation of Fbln2 compared to IDC (P < 0.001), ILC (P < 0.0001), mixed ductal carcinoma (P < 0.001), and invasive breast cancer (P < 0.05)." (PMID 39110274, 2024).
Kaposi's sarcoma (3 papers, 2018 to 2021). A malignant neoplasm characterized by a vascular proliferation which usually contains blunt endothelial cells. "In Kaposi’s sarcoma, the expression of fibulin-2 is decreased (along with the expression of fibulin-3 and -5), supporting the notion that a lower expression of fibulin-2 stimulates the wild proliferation, invasion, and migration of the cells." (PMID 34063320, 2021).
liver fibrosis (3 papers, 2016 to 2025). "Wt1+ fibroblasts displayed distinct expression of genes, such as Scara5, Fbln2, Adgrd1, and Osr1 (encoding the odd-skipped related transcription factor 1) that has been linked to liver fibrosis, and mesenchymal collagen production (Fig. EV3E)." (PMID 40954217, 2025). "In two independent studies of Collagen-α1(I)-green fluorescent protein (Col1a1GFP) mice with induced liver fibrosis, Fibulin 2, Thy-1 and elastin were overexpressed in cells considered as activated portal fibroblasts." (PMID 27065888, 2016).
pulmonary fibrosis (3 papers, 2023 to 2024). Chronic progressive interstitial lung disorder characterized by the replacement of the lung tissue by connective tissue, leading to progressive dyspnea, respiratory failure, or right heart failure. "We found significant increases in lung mRNA for Fibulin 1 and Fibulin 2, which have been implicated in pulmonary fibrosis." (PMID 37761959, 2023). "Related to these processes, fibulin-2 may also promote fibroblast proliferation and migration and thus be involved in ECM deposition associated with idiopathic pulmonary fibrosis, a chronic progressive lung disease." (PMID 38396702, 2024).
urothelial carcinoma (3 papers, 2020 to 2023). A malignant neoplasm derived from the transitional epithelium of the urinary tract (urinary bladder, ureter, urethra, or renal pelvis). "Correlations between FBLN2 expression and other important clinicopathological parameters in urothelial carcinomas." (PMID 33194662, 2020).
adenoma (2 papers, 2010 to 2022). A neoplasm arising from the epithelium. "FBLN2 similar to DBC1 demonstrated very high frequency of methylation in colorectal tumours, adenomas and corresponding normal samples." (PMID 20205715, 2010).
Alzheimer disease (2 papers, 2024). A progressive, neurodegenerative disease characterized by loss of function and death of nerve cells in several areas of the brain leading to loss of cognitive function such as memory and language. "Four SNPs are mapped to FBLN2, ADAM 10, NHSL1, and ST3GAL1 genes previously associated with Alzheimer Disease." (PMID 38291454, 2024).
astrocytoma (2 papers, 2019 to 2022). "Fibulin-2 seems to be associated with advanced high-grade astrocytomas." (PMID 36048342, 2022). "Fibulin-1 (FBLN1) was described as being up-regulated in high-grade astrocytoma, and Fibulin-2 (FBLN2) and Fibulin-5 (FBLN5) was described as being down-regulated in grade II/III/IV compared with grade I astrocytoma." (PMID 31357616, 2019). "Fibulin-2 role in GBM progression has not been established yet, but it was found associated with advanced clinical stages in II/III/IV grade astrocytomas." (PMID 36048342, 2022).
bladder cancer (2 papers, 2010 to 2020). "To further confirm the initial observations, we examined the Oncomine database for FBLN2 expression in bladder cancers." (PMID 33194662, 2020).